CDH1 (cadherin 1)
Diseases named in the same sentence as CDH1 in open-access papers (continued):
Sharing a sentence is not in itself a finding about the gene and the disease.
cancer (4,684 papers, 1992 to 2026). A tumor composed of atypical neoplastic, often pleomorphic cells that invade other tissues. "The downregulation of CDH1 during EMT has traditionally been associated with an enhanced metastatic potential by enabling cancer cell dissociation and invasion." (PMID 41459333, 2026). "Despite these measures, the consensus remains that PTG is the superior approach for managing CDH1 mutation carriers due to the high likelihood of undetected cancer." (PMID 40585607, 2025). "Our findings indicate that a broader panel of cancer predisposition genes, beyond CDH1 and CTNNA1, should be included in gene panels to investigate germline variants in patients with GC." (PMID 40446793, 2025). "Recent advances in genomic sequencing have identified novel CDH1 variants, expanding our understanding of the gene’s role in cancer predisposition." (PMID 40366456, 2025). "Such mutations in CDH1 lead to the loss or dysfunction of E-cadherin, thereby facilitating cancer cell invasion and metastasis." (PMID 40861444, 2025). "New CDH1 variants continue to emerge, challenging current classifications of pathogenicity and cancer risk." (PMID 40366456, 2025). "Research is investigating CDH1 deficiency and its influence on cancer cell behavior, exploring its potential as a therapeutic target." (PMID 40809316, 2025). "Various types of mutations in the CDH1 gene can lead to the disruption of its protein function, contributing to cancer susceptibility." (PMID 40585607, 2025). "Mutations in the CDH1 gene have been associated with a higher risk of certain types of cancer, particularly stomach (gastric) cancer and lobular breast cancer, which is known as hereditary diffuse gastric cancer syndrome." (PMID 39996890, 2025). "For instance, the predicted negative regulation of the EMT-associated gene CDH1 by the miR-200 family is a cornerstone of cancer metastasis research." (PMID 40924781, 2025). "Consistently, an established cancer derived BARD1-binding-deficient-BRCA1 C61G mutant still interacts with Cdh1." (PMID 41359628, 2025). "This dual surveillance strategy reflects the multifaceted cancer risks associated with CDH1 mutations and aims to provide comprehensive management for affected individuals." (PMID 40585607, 2025). "This highlights the gap in data documentation through databases and research in the region to provide a better understanding of the role of CDH1 mutations in cancer predisposition." (PMID 41049353, 2025). "CDH1 plays a crucial role in the signal transduction pathways associated with cancer, particularly in tumors linked to neuroactive ligand–receptor interactions." (PMID 40331986, 2025). "CDH1 gene mutations encoding aberrant E‐cadherin proteins have been found in patients with cancer, which is experimentally supported by the phenotypes of a mouse model with enhanced tumorigenesis harboring a dominant negative form of E‐cadherin." (PMID 40623872, 2025). "For example, SNAIL and SLUG, members of the Snail protein family, repress the E-cadherin gene CDH1, which leads to the loss of cell–cell adhesion and increased motility of cancer cells." (PMID 40362280, 2025). "The largest single-centre experience reported for CDH1 pathogenic carriers who underwent PTG was from the Memorial Sloan Kettering Cancer centre consisting of 101 patients." (PMID 38339225, 2024). "Since loss of adhesion in many types of cancer is often attributed to decreased E-cadherin expression, Cdh1 expression was quantified by real-time PCR and showed a slight transcriptional upregulation in response to H. pylori infection." (PMID 39000189, 2024). "This downregulation of CDH1, in turn, is associated with increased cancer cell migration and invasion." (PMID 38707537, 2024).
cancer (continued). "Co-treatment of mice with the FAK inhibitor and ROS1 inhibitors also showed synergistic effects against CDH1-deficient cancers." (PMID 37324948, 2023). "Recently, the potential role of CDH1 in metastasis as a prognostic indicator has been investigated, as loss or reduction of its expression correlates with increased aggressiveness of cancers." (PMID 37174083, 2023). "ROS1 inhibition results in synthetic lethality in CDH1-deficient cancers, but often leads to adaptive resistance." (PMID 37324948, 2023). "In the present study, hyperactivation of FAK signaling was also found to be related to the adaptive resistance to a ROS1 inhibitor in the treatment of CDH1-deficient cancers." (PMID 37324948, 2023). "FAK inhibition, either by FAK inhibitors or by knocking down its expression, resulted in higher cytotoxicity potency of the ROS1 inhibitor in CDH1-deficient cancer cell lines." (PMID 37324948, 2023). "Factors influencing this decision include confirmatory genetic testing for CDH1 mutation, positive biopsy results, and perceived familial cancer burden." (PMID 35499650, 2023). "One Crohn-related non-SRC-type SB-PCC harbored a frameshift deletion of the CTNN1A gene, along with KRAS and MYC amplifications, while a CDH1 mutation was identified in another cancer (SRC type, Crohn related)." (PMID 36812376, 2023). "Any alteration in CDH1 gene expression is implicated in several cancer‐related signaling pathways, such as the Wnt signaling pathway, which has been identified in diverse cancer types." (PMID 37901797, 2023). "There are 3 main therapeutic approaches which include targeting downstream signalling pathways to inhibit cell proliferation, reversing second hit mechanism of the wild-type CDH1 allele and a synthetic lethal approach to induce cancer cell death." (PMID 36869400, 2023). "The Slovenian population was statistically significantly (p < 0.05) enriched for pathogenic variants in ATM, BRCA1, and CDH1 genes when compared to the gnomAD non-cancer control population." (PMID 37002323, 2023). "Cdh1 gene (encoding E-cadherin), one of the marker genes associated with the epithelial features of cancer cells, was among the most downregulated genes in the Vcam1KO cells." (PMID 36828890, 2023). "Here, we demonstrate that upregulation of the FAK activity accompanies the emergence of resistance to ROS1 inhibitor therapy in gastric and breast CDH1-deficient cancers." (PMID 37324948, 2023). "The loss of E-cad expression has been considered a hallmark of cancer progression and metastasis via loss of heterozygosity of the chromosomal region 16q22.1 containing the CDH1 locus, nonsense mutations, or promoter methylation." (PMID 37189027, 2023). "CDH1 can mediate connections between cancer cells, and loss or deficiency of CDH1 expression weakens cell‒cell adhesion, facilitating the dissociation of cells from surrounding tissues." (PMID 37885030, 2023). "Cdh1 (Cadherin 1) encodes E-cadherin, a classical cadherin regulating cell–cell adhesions, tissue formation, and suppression of cancer." (PMID 37623249, 2023). "CRC is the fourth most common cancer phenotype in the world, but a very rare event in germline CDH1 mutation carriers with HDGC syndrome." (PMID 35277969, 2022). "We report for the first time the prevalence of P/LP CDH1 variants across several cancers and show significant enrichment in CDH1 P/LP variants for patients with CSRCC, DGC, and LBC across various ethnicities." (PMID 34949788, 2022). "The CDH1 mutation and abnormal expression of CDH1 are associated with therapy resistance in several types of cancer." (PMID 36551262, 2022). "We screened for CDH1 variant enrichment in each cancer relative to a cancer-free population from The Genome Aggregation Database version 3 (gnomADv3)." (PMID 34949788, 2022).
cancer (continued). "Herein, we discuss the multiple cancer phenotypes that are currently known to be associated with germline CDH1 pathogenic mutations and their possible implications for risk containment." (PMID 35277969, 2022). "Studies have shown the association of different types of cancers with CDH1 rs3743674 polymorphism, however some other reports have shown no significant relation." (PMID 36910346, 2022). "CDH1 not only mediates the cancer progression but also serves as a risk factor and predictor of poor prognosis in BC." (PMID 35784532, 2022). "Down-regulation or loss of E-cad encoded by CDH1 is also known to contribute to malignant tumor invasion and metastasis." (PMID 35784532, 2022). "EZH2 can combine with the CDH1 (encoding E-cadherin) promoter to decrease the expression of E-cadherin and promote the metastasis and invasion of cancer cells." (PMID 35505294, 2022). "CDH1 loss-of-function is assumed to be an initiating event in early carcinogenesis, and it is thought to contribute to cancer progression by increasing cell proliferation and invasion ability of the neoplastic cells." (PMID 36556227, 2022). "Identification of individuals with a CDH1 P/LP variant provides opportunities for cancer risk reduction and early detection." (PMID 36246616, 2022). "Hypermethylation of the CDH1 gene is a recognized secondary event to the gene mutation, thus contributing synergistically to CDH1 inactivation in different cancer types." (PMID 36556227, 2022). "Herein, we mapped the landscape of pathogenic and likely pathogenic (P/LP) germline variants in CDH1 across various cancers and ethnicities." (PMID 34949788, 2022). "For instance, CDH1 (encodes E‐cadherin) showed similar levels in all three normal cell lines as well as in H157 and SqCC/Y1 carcinoma lines." (PMID 35000271, 2022). "Second, we perform a systematic review comparing the detection rate of cancer foci via endoscopy with random biopsies against the standardized Cambridge Protocol in asymptomatic patients with a documented CDH1 mutation." (PMID 34073553, 2021). "This is associated with a germline mutation in the E-cadherin gene (CDH1) and an 80% lifetime cancer risk." (PMID 34249318, 2021). "play a progressive synergic role with CDH1 missense mutations in BC development (as in other cancers)." (PMID 34066044, 2021). "Of note, CDH1 mutations have been detected in many other types of cancer including breast, prostate, colorectal, ovarian and thyroid cancers." (PMID 34419139, 2021). "Third, in lieu of any comprehensive database that tracks outcomes of CDH1 mutation carriers, we calculate an estimated secondary cancer risk among patients with sporadic gastric SRCCs, using the Surveillance, Epidemiology, and End Results (SEER) database." (PMID 34073553, 2021). "They sequenced 94 genes involved in cancer predisposition, identifying eight different CDH1 pathogenic/likely patogenic mutations in nine different patients with DGC and a mean age of almost 40 years." (PMID 34201547, 2021). "The ubiquitous availability of cancer panels has led to the identification of an increasing amount of “incidental” CDH1 genetic variants that pose a serious clinical challenge." (PMID 34503169, 2021). "In fact, histologically detectable cancer foci have been discovered by endoscopic multiple sampling in a large portion of individuals with germline CDH1 variants, and one study succeeded in identifying HDGC based on endoscopic observations." (PMID 34267306, 2021). "CDH1 encodes e-cadherin, a cell–cell adhesion protein important in epithelial cell function, maintenance of tissue architecture and cancer suppression." (PMID 34639015, 2021). "Our findings proved to impact management of individuals harboring CDH1 germline alterations and to be crucial for cancer risk estimation." (PMID 34503169, 2021).
cancer (continued). "Analysis of 624 cancer-related genes revealed that the CDH1 gene had the highest density of germline rare variants (ratio of variant frequency to the length of the gene)." (PMID 34267306, 2021). "Meanwhile, we have observed in clinical practice a progressive increase of the germline mutation screening test, through genetic panel, involving the search of dozens of genes, including CDH1, for several families with apparent risk of another cancer." (PMID 34008707, 2021). "DGC is the hallmark cancer of this genetic predisposition, but several other cancers are associated with these CDH1 mutations." (PMID 34066044, 2021). "The fourth molecular subtype shows a diffuse morphology of cancer cells due to the frequent loss of the cell adhesion molecule cadherin 1 (CDH1)." (PMID 33223522, 2021). "Induction of EMT in concert with loss or dysfunction of CDH1 is strongly linked with tumorigenesis and metastatic competence in numerous cancers." (PMID 33420368, 2021). "Among the genes in the AJ cassette defined above, we focused our efforts on CDH1 encoding E-cadherin, because it is a major cancer gene, its expression is known to activate the Hippo pathway, and because E-cadherin is a key constituent of AJs." (PMID 32641858, 2020). "In different types of cancer increased invasiveness is connected with downregulation of the E-cadherin-encoding gene (CDH1)." (PMID 33076339, 2020). "It is encoded by the gene CDH1 located on chromosome 16q-22 and decreased expression of E-cad has been correlated with cancer progression." (PMID 32102518, 2020). "The E-cadherin (CDH1) gene, encoding the E-cadherin protein, is a cancer predisposition gene predominantly mutated in hereditary diffuse gastric cancer (HDGC)." (PMID 32373223, 2020). "The autosomal dominant inheritance pattern of these mutations requires a second-hit for cancer progression and this second hit usually in a germline CDH1 mutation was found to be due to promoter hyper methylation." (PMID 33062523, 2020). "A CDH1 mutation (frame shift indel) was detected only in one H. pylori-uninfected cancer lesion (case 6)." (PMID 32727394, 2020). "CDH1 deletions have been shown to cause cancers with immune cell infiltration, activation of targetable immune checkpoint pathways and gene expression related to T-regulatory (Treg) cell signaling." (PMID 33408272, 2020). "Hereditary diffuse gastric cancer (HDGC) is a cancer susceptibility syndrome caused by germline pathogenic variant in CDH1, the gene encoding E-cadherin." (PMID 32664545, 2020). "The wide variety of CDH1-associated activities demonstrates its complicated role in cancer progression, and warrants further investigation." (PMID 32805721, 2020). "CDH1 encodes for the adhesion molecule E-cadherin, and its loss triggers cancer-related pathways such as β-catenin and Wnt-, EGFR-, and mTOR-dependent signaling cascades." (PMID 32752096, 2020). "The introduction of MGPT for hereditary cancer susceptibility has caused an increase in the number of CDH1 mutations detected." (PMID 32560361, 2020). "Further the expression of the top significant DUBs in both cancer types was simultaneously inversely correlated with the expression of an additional molecular marker, E-cadherin (CDH1), whose loss is considered to be fundamental for EMT." (PMID 32636467, 2020). "A CDH1 mutation (frame shift indel) was detected in one H. pylori-uninfected cancer not only in the mucosal SRCC but also in the invasive portion." (PMID 32727394, 2020). "The aberrant expression of CDH1 (expresses the protein E-cadherin) is associated with increased overall survival in various cancers, however, E-cadherin expression in PDAC progression has remained elusive." (PMID 33110361, 2020).
cancer (continued). "Loss of CDH1 activity is a common occurrence in cancer development, and the generation of heterozygous CDH1+/- mice that are haploinsufficient incur greater rates of cancer formation." (PMID 32805721, 2020). "Recently, Lo et al17 reported that the location and type of germline CDH1 variants are related to the age of cancer onset and risk of concomitant cancer in the HDGC families." (PMID 31892987, 2020). "CDH1, a cancer susceptibility gene, encodes for E-Cadherin, a cell adhesion protein regulating epithelial architecture and cellular polarity." (PMID 33322525, 2020). "CDH1 deletions have been shown to cause cancers with immune cell infiltration, activation of targetable immune checkpoint pathways and gene expression related to T-regulatory (Treg) cell signaling, suggesting immune checkpoint potential therapeutic options." (PMID 33408272, 2020). "The clinical relevance of differentiating craniofacial from cancer phenotypes is substantial, given the possibility of identifying CDH1 variants in genomic investigations for CL/P." (PMID 32260281, 2020). "The loss of CDH1 expression promotes cancer metastasis through the epithelial–mesenchymal transition (EMT) mechanism." (PMID 31431673, 2019). "Without the targeted interventions offered to the 15 cases that were likely diagnosed as a result of being a known CDH1 mutation carrier, it is unlikely they would have presented until their cancers had progressed and symptoms emerged." (PMID 29589180, 2019). "E-cadherin, a component of epithelial adherens junction, is encoded by CDH1 and becomes lost in cancer cells undergoing EMT." (PMID 31440236, 2019). "These inverse effects of regulation of focal adhesion, CDH1 and estrogen receptor in cancer and AD are consistent with a possible association of these pathways to the inverse comorbidity patterns observed." (PMID 31247897, 2019). "Patients with hereditary diffuse gastric cancer (germline CDH1 mutation) undergo prophylactic gastrectomy due to the challenge in early diagnosis of this type of carcinoma." (PMID 31638990, 2019). "CDH1 is a key cell-to-cell adhesion molecule; loss of CDH1 expression in carcinomas will dissemble epithelial cell sheets." (PMID 31105876, 2019). "CDH1 encodes the cell adhesion molecule E-cadherin, which is strongly implicated in invasion and metastasis in cancers of epithelial origin." (PMID 30069008, 2018). "The overlap also confirmed strong association of JARID1B expression with E-cadherin downregulation, a hallmark of EMT, which was consistent with enrichment of genes known to be downregulated following E-cadherin loss in cancer (ONDER_CDH1_TARGETS_2_DN)." (PMID 29507668, 2018). "We chose CDH1 mutations as an example to elucidate how gene mutations were associated with cancer pathway alterations." (PMID 29520031, 2018). "Firstly, the COSMIC portal of somatic mutations in cancer was used to retrieve the mutations listed in the CDH1 gene." (PMID 28934230, 2017). "Loss of CDH1 expression, or CDH1 dysfunction, contributes to the loss of cell–cell interaction which stimulates cancer cells to gain an invasive cell phenotype and metastasis." (PMID 28070169, 2017). "If mutations induce cancer cells to detach from the primary tumor, then one would expect the prevalence of primary carcinomas with a CDH1 or CTNNB1 mutation to be greatest for anatomic sites that are most likely to metastasize." (PMID 29156750, 2017). "TSG CDH1 is termed as epithelial cadherin (E-cadherin) or cadherin-1 and is associated with the invasion and metastasis of cancer." (PMID 29100425, 2017). "For every site, the SEER proportion of patients diagnosed with regional or distant disease was larger than our observed prevalence of carcinomas with at least one CDH1 mutation." (PMID 29156750, 2017). "Across all anatomic sites, 4% of carcinomas had at least one CDH1 mutation and 4% of carcinomas had at least one CTNNB1 mutation." (PMID 29156750, 2017).